TBPL2 (TATA-box binding protein like 2)
Description:
Transcription factor required in complex with TAF3 for the differentiation of myoblasts into myocytes. The complex replaces TFIID at specific promoters at an early stage in the differentiation process (By similarity).
Synonyms: TBP2; TRF3
Tractability: PROTAC: ubiquitination databases record sites on it.
Gene: Protein-coding gene on chromosome 14 (55,414,210 to 55,456,726, reverse strand). Ensembl gene ENSG00000182521.
Subcellular location: Cytoplasm; Nucleus
Pathways (Reactome):
Developmental Biology: Germ layer formation at gastrulation
Gene Ontology:
Molecular function: RNA polymerase II general transcription initiation factor activity; DNA binding
Biological process: DNA-templated transcription initiation; transcription by RNA polymerase II
Cellular component: cytoplasm; nucleus
Genetic constraint (gnomAD): Loss-of-function variants: 31 observed, 30.36 expected, observed/expected ratio (o/e) 1.02, 90% interval 0.77 to 1.38. The upper end of that interval is the gene's LOEUF score, 1.38, which puts it in group 5 of 6, group 1 being the genes least tolerant of losing a copy. Missense variants: 398 observed, 402.55 expected, observed/expected ratio (o/e) 0.99, 90% interval 0.91 to 1.07. Synonymous variants: 150 observed, 154.64 expected, observed/expected ratio (o/e) 0.97, 90% interval 0.85 to 1.11.
Homologues: Orthologues: chimpanzee TBPL2 (99% identical), macaque TBPL2 (97% identical), dog TBPL2 (86% identical), pig TBPL2 (84% identical), rabbit TBPL2 (83% identical), guinea pig TBPL2 (80% identical), tropical clawed frog tbpl2 (70% identical), mouse Tbpl2 (69% identical), rat Tbpl2 (68% identical), zebrafish tbpl2 (60% identical). Paralogues in human: TBP (60% identical), TBPL1 (22% identical).
Diseases named in the same sentence as TBPL2 in open-access papers:
TBPL2 is named in the same sentence as 9 diseases in open-access papers, as found by Europe PMC text mining. Sharing a sentence is not in itself a finding about the gene and the disease. The quoted sentences say what the papers report.
female infertility (2 papers, 2024). Diminished or absent ability of a female to achieve conception. "Previous studied identified that variants in TBPL2 caused oocyte maturation defects and oocyte maturation defects, leading to female infertility." (PMID 38643161, 2024). "The TBPL2 locus has not been previously associated with female infertility or any disorder associated with infertility in GWASs." (PMID 39566493, 2024).
Infertility (1 paper, 2024). "According to data from gnomAD (v.3.1.2), loss-of-function mutations in TBPL2 are rare, with the stop-gained mutation associated with infertility in this study being an exception." (PMID 39566493, 2024). "Apart from our findings, there are only scattered reports of coding mutations in TBPL2 detected in women with infertility." (PMID 39566493, 2024). "Through a large-scale GWAS of 22,849 women with infertility and nearly 199,000 control individuals from FinnGen, we uncovered a rare TBPL2 mutation with a strong impact on infertility." (PMID 39566493, 2024). "According to the registry data, only four homozygous women for the TBPL2 mutation had children, and all of them had received infertility treatment." (PMID 39566493, 2024). "Some loci, such as TBPL2, are uniformly associated with infertility in both early- and late-onset affected individuals, but we identified two loci uniquely associated with infertility only among women diagnosed before age 30 and one locus associated with late-onset disease." (PMID 39566493, 2024). "In contrast, the two recessive loci (near TBPL2 and PKHD1L1) were specifically associated only with infertility." (PMID 39566493, 2024). "In our follow-up analyses, the TBPL2 mutation was associated only with infertility and no other diseases." (PMID 39566493, 2024).
TBPL2 also shares sentences with these, for which no sentence is quoted: bladder cancer (3 papers); tumor (3); acute pancreatitis (1); diabetic nephropathy (1); myocardial infarction (1); pancreatitis (1); urothelial carcinoma of the (1).